IL1A (interleukin 1 alpha)
Diseases named in the same sentence as IL1A in open-access papers (continued):
Sharing a sentence is not in itself a finding about the gene and the disease.
anemia (4 papers, 2020 to 2024). A reduction in the number of red blood cells, the amount of hemoglobin, and/or the volume of packed red blood cells. "Maternal anemia (enrollment Hb level < 11 g/dL) was significantly associated with greater odds of elevated IL-1α (aOR = 1.92, 95% CI: 1.04, 3.54)." (PMID 34836049, 2021). "The odds ratios (ORs) and 95% confidence intervals for elevation (top quartile) of IL-1α, IL-1β, IL-6, IL-8, and CRP in umbilical cord blood are shown for maternal nutrition (anthropometrics and anemia) and infections in pregnancy." (PMID 34836049, 2021). "Moreover, hepcidin level may be increased with age, independent of IL-6, if kidneys fail to clear hepcidin efficiently, or if other inflammatory cytokines, such as IL-1α or β induce its production, suggesting that IL-6 and hepcidin possibly led to the development of anemia with age independently." (PMID 32095285, 2020). "Chronic inflammation has been shown to induce anemia, and we hypothesized the increase in TNFα, MCP-1, and IL-1α in the BM of Sost−/− mice would result in a decrease of mature erythrocytes (red blood cells, RBC)." (PMID 34502021, 2021).
Anorexia (4 papers, 2019 to 2022). Lack of desire to eat (loss of appetite). "Indeed, cytokines (e.g., TNF-a, IL-1a, IL-1b and IL-6) can directly cause neuronal apoptosis and produce a stereotyped cluster of nonspecific signs such as impaired concentration, anorexia, fatigue, diminished motivation, depression, and anorexia." (PMID 35964069, 2022).
chlamydial infection (4 papers, 2014 to 2022). "On the one hand, IL-1α combined with DNA of host cells enhances the expression of IL-8, mediating host inflammation in the early stage of chlamydial infection." (PMID 34093528, 2021). "Current evidence shows that IL-1α can affect the secretion and maturation of IL-8 during chlamydial infection in two ways." (PMID 34093528, 2021). "Studies investigating the cytokine and chemokine response to chlamydial infection have shown up-regulation of IL-1α, IL-6, IL-11, TGF-β1, GM-CSF, GRO-α and IL-8 in C. trachomatis-infected HeLa cells." (PMID 25019934, 2014). "Furthermore, CT-infected A2EN basolateral supernatants further enhanced HIV production, but apical supernatants did not, despite the finding that apical IL1α increases after chlamydial infection." (PMID 26730599, 2016).
cholesteatoma (4 papers, 2020 to 2024). A pathologic process characterized by the proliferation of keratinizing squamous epithelium resulting in the accumulation of keratin and cells in the middle ear and/or mastoid. "In cholesteatoma, IL-1α is associated with the destruction of the surrounding middle ear bone and cholesteatoma growth." (PMID 38535082, 2024). "Bone resorption and destruction was also shown to be positively correlated to inflammation, the presence of bacterial lipopolysaccharides (LPS), and expression of inflammatory mediators like TNFα, IL-1α, and IL-6 in cholesteatoma." (PMID 31947538, 2020). "NF-κB target genes particularly include pro-inflammatory cytokines like TNFα, IL-1α, IL-1ß, IL-6, and IL-8 and were shown to be upregulated in cholesteatoma tissue." (PMID 31947538, 2020). "Furthermore, IL-1α induces osteoclast function and increases bone matrix degradation, and it is known that MMP-2 and MMP-9 also cause bone matrix degradation for patients with cholesteatoma." (PMID 38535082, 2024). "This enhanced expression in vitro fits to the higher expression of KGF, IL-1α and HGF detected in vivo in cholesteatoma tissue when compared to auditory canal skin." (PMID 33627146, 2021). "In detail the expression of the cytokines, e.g. IL-1α IL-1β and IL-6, TNF-α, GM-CSF and the chemokine IL-8, is elevated in cholesteatoma." (PMID 33627146, 2021). "The intercorrelations we found among IL-1α and MMP-2 and MMP-9 may support the theory that MMP activity is also regulated by IL-1α in cholesteatoma tissue." (PMID 38535082, 2024). "In contrast with the strong positive correlation between IL-1α and IL-10 in both groups of cholesteatoma, we found a very strong but negative correlation between IL-1α and IL-10 in the control group." (PMID 38535082, 2024). "Upon LPS challenge, we could detect a significantly higher expression of IL-1α, IL-1β, IL-6 and IL-8 in stem cells and of TNF-a, GM-CSF and CXCL-5 in stem cells and fibroblasts derived from cholesteatoma." (PMID 33627146, 2021). "When comparing the cells derived from cholesteatoma tissue with the cells from auditory canal skin, we could observe a significant upregulation of the two growth factors KGF and IGF-2 and a similar trend for IL-1α and HGF." (PMID 33627146, 2021). "Hence the presence of inflammatory mediators in cholesteatoma tissue was studied and exhibits a higher presence of the cytokines TNFα, IL-6, IL-8, IL-1α, and IL-1ß in comparison to non-inflamed external auditory canal skin tissue." (PMID 31947538, 2020).
colorectal adenocarcinoma (4 papers, 2016 to 2025). The most common type of colorectal carcinoma. "A recent work has elucidated a decreased tumour expression of IL1A in colorectal adenocarcinoma, which indicated the potential role of IL1A in the etiology of CRC." (PMID 30819119, 2019). "We also interrogated the co-expression of the reported genes on the same data set (17157 genes from 244 colorectal adenocarcinoma cases); strikingly, IL1B, IL8 and CXCL1 display the highest correlation with IL1A, with a Pearson correlation of 0.66, 0.55 and 0.51 respectively." (PMID 27708224, 2016).
contact dermatitis (4 papers, 2016 to 2024). An inflammatory skin condition caused by direct contact between the skin and either an irritating substance or an allergen. "Phenol produces an inflammatory response with characteristic of contact dermatitis to stimulate the breakdown of keratinocytes with release of cytokines (IL-1α, TNF-α and IL-8)." (PMID 27916942, 2016). "In 2009, there was a case report about irritant contact dermatitis caused by a methylrosaniline patch at the therapeutic concentration of 0.5%; this percentage is close to the 12.5 μM concentration which we observed a significant IL-18 elevation, but not IL-1α." (PMID 32154236, 2020).
cystitis (4 papers, 2011 to 2021). Inflammation of the urinary bladder. "Acute cystitis has been associated with an increase in urine IL-1α, GRO-α, IL-1β, IL-6, IL-8 and TNF-α compared to sterile samples." (PMID 22140570, 2011). "Inhibition of caspase 1/11 protected superinfected mice from chronic cystitis, suggesting a role for cytokines downstream of caspase activation including IL-1α and IL-1β, identified in our microarray of four-week bladders." (PMID 25569799, 2015). "In previous studies, an IL-1α response was detected in patients with acute cystitis and acute pyelonephritis." (PMID 22140570, 2011). "This was confirmed by examination of the pro-inflammatory factors showing that interleukin (IL)-1α, IL-6 and tumor necrosis factor (TNF)α levels in the urinary bladder were increased with cystitis." (PMID 25486122, 2014).
disseminated candidiasis (4 papers, 2015 to 2021). Systemic candidiasis occurs when Candida yeast enters the bloodstream and may spread (becoming disseminated candidiasis) to other organs, including the central nervous system, kidneys, liver, bones, muscles, joints, spleen, or eyes. "In contrast, during disseminated candidiasis Il1a-deficiency was associated with decreased anti-fungal activity of leukocytes." (PMID 25629406, 2015). "Additionally, impaired control of pulmonary histoplasmosis and disseminated candidiasis was observed in Il1r1-deficient and Il1a/Il1b-doubly deficient mice, respectively." (PMID 25629406, 2015). "Both IL-1α and IL-1β have also been shown to play an important role in disseminated candidiasis, and IL-1 signaling has shown to contribute to host resistance against pulmonary histoplasmosis and Coccidioides sp." (PMID 29403476, 2017).
encephalitis (4 papers, 2020 to 2025). An acute inflammatory process affecting the brain parenchyma. "The expression of IL-1α and IL-1β in the CSF correlated with symptoms (inflammation and fever) linked to both encephalitis and meningitis groups." (PMID 40517242, 2025). "Menopause is a physiological condition that triggers encephalitis, leading to the production of cytokines such as interleukin-1β (IL-1β), IL-1α, and IL-6." (PMID 40292265, 2025). "We detected higher levels of TNF-α, IL-10 and GM-CSF in CSF of paraneoplastic anti-NMDARE patients compared to the negative symptom control group (P < 0.05)and lower level of IL-1α and VEGF-A compared to the anti-NMDAR encephalitis patients(P < 0.05)." (PMID 32771066, 2020).
Glucose intolerance (4 papers, 2020 to 2025). Glucose intolerance (GI) can be defined as dysglycemia that comprises both prediabetes and diabetes. "A recent report indicates a possible role of IL-1α in promoting adiposity-induced glucose intolerance and hepatic de-novo lipogenesis." (PMID 34658856, 2021).
HIV-1 infection (4 papers, 2012 to 2025). The type species of lentivirus and the etiologic agent of acquired immunodeficiency syndrome (AIDS). "For example, IL-1α, IL-10, CCL2, LMNA, and VCAM1, the target genes identified in this study, have been reported to be associated with HIV-1 infection and pathogenesis." (PMID 38110484, 2023). "Instead, expression of IRF5-regulated genes IL1A and IL23A was significantly downregulated in response to HIV-1 infection in MDMs from younger donors." (PMID 40493408, 2025). "In this regard, it has been reported that HIV-1 infection augments L. infantum multiplication in MDMs, and that, conversely, Leishmania enhances HIV-1 replication through inducing the production of TNF-α and IL-1α." (PMID 22412921, 2012). "In contrast, the apparent dichotomous observation of greatly increased barrier dysfunction and leakage along with decreased TNF-α and IL-1α production after treatment with MPA and HIV-1 challenge indicate that MPA may still lead to enhanced HIV-1 infection due to increased viral entry." (PMID 31546582, 2019).
infarction (4 papers, 2015 to 2025). A localised pathological necrosis of tissue resulting from obstruction of the blood supply usually by a thrombus, an embolus, or vascular torsion. "In the animal model of AMI, the injured myocardial cells released interleukin-1 alpha (IL-1α), while interleukin-1 beta (IL-1β) increased after infarction." (PMID 34568491, 2021). "Although IL-1α and IL-1β remain the best-studied members of the family, emerging evidence implicates IL-18 and IL-33 in regulation of the post-infarction inflammatory reaction." (PMID 26273700, 2015).
infertile (4 papers, 2009 to 2024). "By countering the functions of gonadotropins, IL-1β impairs follicle development and ovulation in a way that complements the actions of IL-1α, contributing to infertility." (PMID 37062827, 2023). "By opposing the action of estradiol, IL-1α consequently prevents normal development of follicles and repair of the endometrium after menstruation contributing to infertility typically seen in PCOS." (PMID 37062827, 2023). "We assessed the potential role of proinflammatory cytokines (TNF-α, IL-6 and IL-1α) and microRNAs (miR-146a-5p, miR-34a-5p and miR-23a-3p) in the seminal plasma of infertile men compared to controls, evaluating their correlation with seminal and biochemical parameters." (PMID 34319544, 2021). "Consequently, we investigated the presence of mRNA encoding IL-1 in the endometrium of animals with disparate disease outcomes and found that during Period 1, infertile animals had higher levels of IL1A and IL1B, and their cognate IL1R2, compared with fertile animals." (PMID 19476661, 2009). "The ratio of IL1A or IL1B to IL10 decreased between Period 1 and 2 in infertile animals (P < 0.05)." (PMID 19476661, 2009). "In summary, in fertile and infertile patients’s seminal plasma, the expression of cytokines (TNF-α, IL-6), miRNAs (miR-146a-5p, miR-34a-5p, miR-23a-3p) and IL-1α protein was not strongly correlated to any standard sperm parameters." (PMID 34319544, 2021).
intestinal inflammation (4 papers, 2013 to 2025). "An alternative hypothesis to support the dichotomous role of IL-1 in IBD is that IL-1α and IL-1β possess opposing roles during the progression of chronic intestinal inflammation." (PMID 23847622, 2013). "Intestinal inflammation involves immune cells of both the innate and adaptive immune systems, and is characterized by marked increases in pro-inflammatory cytokines IL-1β, TNF-α, IL-12, IL-17, IL-1α and INF-γ." (PMID 32998266, 2020).
liver cancer (4 papers, 2018 to 2022). An epithelial or non-epithelial malignant neoplasm that arises from the liver. "At the same time, the content of IL-1α, IL-12 P70, TNF α, IL-1β and IL-6 was significantly reduced, and the content of IL-10 was significantly increased like in the previous liver cancer model." (PMID 34976592, 2022).
liver cirrhosis (4 papers, 2015 to 2024). "An increase of one unit (1 pg/mL) of the IL-1α concentration resulted in 8% increased risk of the liver cirrhosis, an increase of one unit (1 pg/mL) of IL-6 concentration implicated about 5% increased risk, and an increase of one unit (1 pg/mL) of HGF implicated 3% increased risk of liver cirrhosis." (PMID 26448742, 2015). "Another study reported that IL-1α and IL-6 serum levels were significantly increased in alcoholic cirrhosis patients, being correlated with the progression of liver cirrhosis." (PMID 38473721, 2024). "The univariate logistic regression analysis showed that levels of IL-1α, IL-6, and HGF had influenced liver cirrhosis risk (p < 0.001)." (PMID 26448742, 2015). "Further detailed analysis revealed significantly higher IL-1α concentrations in patients with classes B and C liver cirrhosis in comparison with the control group." (PMID 26448742, 2015). "A statistically significant positive correlation was found between concentrations of HGF versus concentrations of IL-1α and IL-6 in the group of patients with liver cirrhosis." (PMID 26448742, 2015). "There was significant positive correlation between HGF, IL6, IL-1α, and stage of liver cirrhosis (p < 0.001) (–8)." (PMID 26448742, 2015). "In this study, elevation of serum Il-1α, IL6, and HGF levels correlated with the progression of liver cirrhosis." (PMID 26448742, 2015).
meningitis (4 papers, 2013 to 2025). A disorder characterized by acute inflammation of the meninges of the brain and/or spinal cord. "The levels of inflammatory cytokines, including interleukin (IL)-1α, IL-1β, IL-6, and TNF-α, in brain tissues were significantly elevated after meningitis induction compared with those in normal controls." (PMID 35888118, 2022). "The results from this study demonstrate a storm of inflammatory cytokines, such as IL1-α, IL-1β, IL-6, IL-18, TNF-α, and INF-γ, in the 24-h meningitis group." (PMID 31901235, 2020). "In the hippocampus, we observed increased levels of pro-inflammatory cytokines, such as IL1-α, IL1-β, IL-6, IL-18, TNF-α, and INF-γ (P < 0.05) in the 24-h meningitis group." (PMID 31901235, 2020). "As expected, in the PFC, we observed increased levels of pro-inflammatory cytokines such as IL1-α, IL1-β, IL-6, IL-17, TNF-α, and INF-γ (P < 0.05) and decreased levels of IL-7, IL-10, and IL-13 (P < 0.05) in the 24-h meningitis group." (PMID 31901235, 2020). "Homologous antibodies to TNF, IL-1α and IL-1β inhibited leukocytosis and brain edema and moderately decreased BBB permeability in this model of meningitis." (PMID 23997430, 2013).
metastatic tumors (4 papers, 2014 to 2023). "And overexpressing IL1α increased the percentage of iliac lymph node metastasis of the xenografted tumors from 50% to 100% and significantly increased the size of the iliac lymph node metastatic tumors by 1.4‐fold." (PMID 37551997, 2023). "More importantly, knockdown of the expression of IL1α, IL1β and IL8 significantly reduced the size of metastatic tumors in the iliac lymph nodes by 81.9%, 68.0%, and 78.5%, respectively." (PMID 37551997, 2023). "The higher number of macrophages and augmented expression of IL-1α and CXC chemokines in highly metastatic tumors versus lower metastatic tumors led us to examine whether IL-1/IL-1R and/or CXC chemokines/CXCR2 were involved in the ability of LNM35 cells to recruit macrophages." (PMID 24924428, 2014).
pemphigus (4 papers, 2008 to 2025). Pemphigus is a group of rare autoimmune diseases that cause blistering of the skin and mucous membranes (mouth, nose, throat, eyes, and genitals).This conditioncan occur at any age, but often strikes people in middle or older age. "Possible mechanisms of phenol-induced pemphigus include the induction of IL-1α and TNF-α release by keratinocytes." (PMID 38213911, 2023). "Phenol groups trigger pemphigus by releasing cytokines such as tumor necrosis factor-alpha (TNF-α) and interleukin-1 alpha (IL-1α) and activating the complement system and proteases, causing acantholysis (e.g., aspirin, rifampin)." (PMID 40599502, 2025). "In experimental models, it was also demonstratedthat IL-1α and TNF-α were able to activate C3 mRNA in keratinocytes cultureafter stimulation with pemphigus antibodies obtained from PV patients." (PMID 18584045, 2008).
penile cancer (4 papers, 2015 to 2025). A primary or metastatic malignant neoplasm that affects the penis. "Besides, IL-1A and IL-1B, which have been identified as the key machineries in inflammation modulation to cause penile cancer, were also successfully enriched in the current GO terms." (PMID 26158897, 2015). "Our findings confirm that penile cancer tissues with elevated IL-1α expression are significantly correlated with advanced TNM prognostic stages." (PMID 41465261, 2025). "Since there is no direct relationship between observed polymorphism and IL-1RN level, our results are the first that show the possible lack of IL-1RN blockage of the local inflammatory function of Il-1A and IL-1B in penile cancer." (PMID 37763742, 2023). "The highest levels were noted for IL-1B and IL-1A (ca. 385 and 165 times, respectively) in penile cancer vs. control group." (PMID 37763742, 2023). "Consequently, IL-1α may serve as an indicator of immune system failure and a potential target for immunomodulatory therapy in patients with penile cancer." (PMID 41465261, 2025).
pneumonitis (4 papers, 2005 to 2022). An inflammatory process affecting the lung parenchyma. "SsRNA stimulation of human leukocytes induced cytokines/chemokines similar to those observed in murine SARS-CoV pneumonitis including IL-1α, IL-1β, IL-6, TNF, CXCL8 (IL-8), CCL2 (MCP-1), CCL3 (MIP-1α), and CCL4 (MIP-1β)." (PMID 23236475, 2012). "Cytokines such as IL-1α, IL-1β, IL-6, and TNF-α are produced in excess and potentiate pathological processes such as pneumonitis and vascular thrombosis." (PMID 35991665, 2022). "The mRNAs detected were for cytokines involved in acute inflammation and the fibrosis of pneumonitis: TNF-α/β, IL-6, IFN-β/γ, IL-6, IL-10, IL-1α/β, IL12 and MIF." (PMID 16336675, 2005).
Salmonella Infections (4 papers, 2018 to 2024). Infections with bacteria of the genus SALMONELLA. "The Salmonella infection significantly altered mRNA levels of pro-inflammatory cytokines (IL-6, IL-1α, IL-1β, and TNF-α)." (PMID 38667028, 2024). "Lymphotactin can trigger the chemokine receptor pathway which can further stimulate multiple pathways such as Salmonella infection to produce IL-1α." (PMID 31852428, 2019).
Sjögren syndrome (4 papers, 2018 to 2024). "Furthermore, interleukin levels such as IL-1a, IL-1b, IL-6, IL-8, TNF-a, and MMP-9 have been detected in Sjogren’s syndrome patients." (PMID 39408709, 2024).